IL1RAP (interleukin 1 receptor accessory protein)
Diseases named in the same sentence as IL1RAP in open-access papers (continued):
Sharing a sentence is not in itself a finding about the gene and the disease.
mesothelioma (1 paper, 2009). A usually malignant and aggressive neoplasm of the mesothelium which is often associated with exposure to asbestos. "Only two immune genes were upregulated in the mesothelioma, one from the TGF-β family INHBE and one from the IL-1 receptor family the IL-1 receptor antagonistic peptide (IL1RAP)." (PMID 19662092, 2009).
myelofibrosis (1 paper, 2019). A partial or complete replacement of the bone marrow stroma by fibrous tissue. "IL1RAP, a gene encoding the IL1 coreceptor, is upregulated in overtly fibrotic MPN and may represent a potential therapeutic target against myelofibrosis via anti-IL1RAP antibodies." (PMID 31071164, 2019).
pancreatitis (1 paper, 2023). Inflammation of the pancreas. "Il33 is expressed during pancreatitis by a small subset (4%) of TFF1/ANXA10+Kras-mutant Gastric module-expressing epithelial cells and is predicted to initiate signaling to Tregs and ILCs (Module T8) by binding with its cognate receptor Il1rl1 and co-receptor Il1rap." (PMID 37167403, 2023).
sarcoma (1 paper, 2025). A usually aggressive malignant neoplasm of the soft tissue or bone. "Notably, in sarcomas it can be stabilized by IL-1 receptor accessory protein (IL1RAP), increasing its antiporter activity and conferring resistance to anoikis and protection against ferroptosis." (PMID 41375047, 2025).
soft tissue sarcoma (1 paper, 2025). A malignant neoplasm arising from muscle tissue, adipose tissue, blood vessels, fibrous tissue, or other supportive tissues excluding the bones. "Multiple additional CAR-T cell and TCR-T cell therapies are currently under preclinical and clinical investigation for various bone and soft tissue sarcomas, targeting antigens that include NY-ESO-1, GD2, interleukin-1 receptor accessory protein (IL1RAP), HER2, and B7-H3." (PMID 41008910, 2025).
squamous cell carcinoma (1 paper, 2025). A carcinoma arising from squamous epithelial cells. "ML identified robust predictive models, highlighting SUV and kurtosis (from PET and CT features, respectively) and the expression levels of TP63, EPHA10, FBN2, and IL1RAP as key tools for distinguishing adenocarcinoma from squamous cell carcinoma." (PMID 40192792, 2025).
thyroid (1 paper, 2024). "Moreover, IL1RAP seemed to be coexpressed with LINC02454 and activated the MAPK pathway in thyroid tumorigenesis." (PMID 39218967, 2024).
thyroid cancer (1 paper, 2024). "Our study showed that IL1RAP was highly expressed in thyroid cancer tissues compared with normal tissues." (PMID 39218967, 2024).
tumor (32 papers, 2012 to 2026). "Ligand-receptor pairs linked to high-risk tumors, including IL1A_IL1RAP, COL5A1_ITGB1, APP_NCSTN, PLAU_ITGA5, AGRN_ITGB1, and LAMC2_ITGA6, were found to be particularly enriched in tumor regions." (PMID 40021759, 2025). "We calculated associations between IL1RAP and individual types of immune cells to determine whether other potential interactions were occurring between IL1RAP and the tumour microenvironment." (PMID 35488454, 2022). "Additionally, we performed GSEA enrichment analysis using tumor-related phenotypes associated with IL1RAP, which revealed significant enrichment in hallmark pathways such as inflammatory response, TNFA signaling via NFKB, KRAS signaling down, and IL6 JAK-STAT3 signaling via." (PMID 40444099, 2025). "Consistent with previous reports, we observed IL1RAP, the nadunolimab target, on tumor cells, immune cells, and stroma cells in all three cancer types." (PMID 40310569, 2025). "Rehman demonstrated that patients in the IL1RAP high-expression group exhibited a worse prognosis and a positive correlation with tumor stem cell activity, findings that were validated in two independent knockdown cell lines." (PMID 40444099, 2025). "IL1RAP expression has been identified on the tumor and stromal cells of multiple tumors, promoting an immunosuppressive microenvironment, and its interaction with IL1A/IL1B has also been specifically targeted in a phase 1b clinical trial." (PMID 40647416, 2025). "IL1RAP is highly expressed in various cancers and plays a multifaceted role in promoting tumor growth, metastasis, and immune escape." (PMID 40444099, 2025). "Single-cell data analysis revealed that IL1RAP plays a critical role in regulating intercellular communication within the tumor microenvironment." (PMID 40444099, 2025). "Eleven of the screening biopsies expressed IL1RAP on tumor, stromal, and immune cells, as identified morphologically." (PMID 40310569, 2025). "further revealed that IL1RAP mediates the interaction between tumor cells and M2-type macrophages following PD-1 treatment, which subsequently alters the neutrophil-to-lymphocyte ratio, contributing to an unfavorable prognosis for patients." (PMID 40444099, 2025). "Conversely, a negative correlation was observed between the production of interleukin 1 alpha (IL1A) by CAFs and the expression of its receptors—IL1R1, IL1R2, and IL1RAP—on tumor cells." (PMID 39519201, 2024). "The overexpression of IL1RAP, which encodes a part of the IL1 receptor heterodimer, underscores the activation of the IL1 signaling pathway within tumor environments." (PMID 38979413, 2024). "Referring to the results after the Backward Stepwise method (the final multivariable Cox proportional hazard model), only three significant predictors remained: tumor size (T), tumor differentiation grade (G), and IL1RAP rs4624606 genotype." (PMID 36682035, 2023). "Overall, IL1RAP appears to be a key membrane‐bound tumour antigen for targeting antibody‐mediated selective treatment." (PMID 35488454, 2022). "In all presently investigated tumours, IL1RAP expression was significantly increased with disease progression." (PMID 35488454, 2022). "The use of ScFv immune phage-display libraries has already shown good results in the development of human therapeutic recombinant antibodies for tumor-targeted therapy EphA2, and in the discovery of ScFv against IL1RAP from a human library." (PMID 36293532, 2022). "IL1RAP is a novel target for antibody therapy, which suppresses tumour cell proliferation in vitro and in vivo." (PMID 35488454, 2022). "IL-1RAP is involved in the different phases of tumor development by activating signaling pathways in cancer cells." (PMID 36499246, 2022). "These included genes known to be expressed by microglia (CCL8, SPP1, IRF7, IL1RAP), macrophages (IL1RN, SPP1, PDPN, IL1RAP, MDK, TFRC, HRH4), and tumor-associated macrophages (IL6, SPP1)." (PMID 22937035, 2012).
tumor (continued). "Furthermore, single-cell sequencing data confirmed the interaction of IL1RAP within the tumor microenvironment." (PMID 40444099, 2025). "IL1RAP plays a key role in the development of cancer, being highly expressed by tumor cells and myeloid cells, and it is involved in the generation, expansion, immunosuppressive function, and recruitment of myeloid cells, such as myeloid-derived suppressor cells and M2 macrophages, into the TME." (PMID 40310569, 2025). "Additionally, IL1RAP facilitates immune evasion by modulating the inflammatory response within the tumor microenvironment." (PMID 40444099, 2025). "Such investigations would clarify whether IL1RAP–PTPRF indeed serves as a unifying link between tumor aggressiveness and immunosuppression, thereby offering a potential avenue for therapeutic intervention." (PMID 40666516, 2025). "Furthermore, IL1RAP enhances inflammatory responses in the tumor microenvironment by mediating the pro-inflammatory effects of IL-1β, thereby supporting tumor growth and invasion." (PMID 40444099, 2025). "Importantly, IL1RAP is overexpressed on tumor cells across various cancers, supporting its potential involvement in carcinogenesis." (PMID 39218967, 2024). "Also, it was revealed that tumor size (T) (p = 0.000), tumor differentiation grade (G) (p = 0.015), and IL1RAP rs4624606 genotype (p = 0.044) were effective variables in multivariable Cox regression analysis prognosing survival of LSCC patients." (PMID 36682035, 2023). "This reduction in H3K18 lactylation attenuates the transcriptional activation of the downstream oncogenes IL1RAP and VASH2, thereby ultimately suppressing tumor malignancy in BC." (PMID 41757512, 2026). "Compared to the control group, the tumor group exhibited higher positive expression of AIFM1, AKT3, and IL1RAP." (PMID 40324259, 2025). "Further analysis of the differential expression of IL-1 family and related genes in normal tissues and HPV- and HPV+ tumor tissues revealed that IL-1α, IL-1β, IL1R1, IL1R2, IL1RL1, IL1RAP, IL1F10, IL-18 and CASP1 were highly expressed in HPV- tumors." (PMID 39461030, 2024). "Directly targeting these molecules especially IL1R1 and IL1RAP significantly impaired the survival and growth of KSHV+ tumor cells, as well as their colony formation on 3-D culture." (PMID 36457850, 2022). "To investigate the selective effects of IL-1a and IL-27 on certain tumor cell lines, we quantified mRNA expression for the subunits of the IL-1a (IL1R1, IL1RAP) and IL-27 receptors (IL27RA, IL6ST)." (PMID 31730010, 2019). "There was no apparent correlation between response and baseline IL1RAP or PD-L1 expression levels in tumor biopsies." (PMID 40310569, 2025). "This article explores the targets that affect local CD8+ T-cell infiltration in tumors and subsequently affect patient prognosis (IL-1A, IL1RAP, IL18RAP, SIGIRR), which may also become a breakthrough in improving tumor treatment efficacy." (PMID 39461030, 2024). "Among them, IL-1α, IL1RAP, IL18RAP, and SIGIRR may affect the prognosis of patients by affecting local CD8+ T cell infiltration in the tumor." (PMID 39461030, 2024). "Moreover, IL1RAP, related to oncogenic signaling and NGFR, displaying an ambivalent role in tumor progression, were upregulated in M." (PMID 35892888, 2022). "In the current study, we found that many of IL1 signaling molecules (e.g., IL1α, IL1β, IL1R1, IL1RAP, IL36, IL36R and IRAKs) were highly activated during KSHV infection or in KSHV+ tumor cells and tissues, indicating the crucial role of these molecules functions in KSHV pathogenesis and oncogenesis." (PMID 36457850, 2022). "A combination of IL1RAP pathway suppression and ICI treatment may promote a TME with improved immune cell functionality, potentially enhancing or restoring an effective anti-tumor response." (PMID 40310569, 2025).
tumor (continued). "Our data showed that directly silencing of IL1 signaling molecules such as IL1R1 and IL1RAP significantly reduced the survival and growth of KSHV+ tumor cells, indicating targeting IL1 signaling may represent a promising strategy for treatment of KSHV-related malignancies." (PMID 36457850, 2022). "The observed overexpression of IL1RAP and the substantial but similar expression levels of IL1R1 in tumor and adjacent non-neoplastic tissues further corroborate the significant role of IL-1 signaling in CRC." (PMID 38979413, 2024).
cancer (20 papers, 2015 to 2025). A tumor composed of atypical neoplastic, often pleomorphic cells that invade other tissues. "IL1RAP was predominantly expressed in cancer-associated fibroblasts (CAFs) and played a critical role in regulating solid tumors." (PMID 40444099, 2025). "Aberrant expression of IL-1RAP has been implicated in various diseases, including multiple types of cancer." (PMID 40444099, 2025). "IL-1RAP plays a crucial role in mediating the IL-1 signaling pathway, which is implicated in inflammation, cancer, neurological disorders, metabolic diseases, and infectious diseases." (PMID 40444099, 2025). "It is important to note that Il1rap, Ifi44, Timd4, Fabp3, and Eno 2 have been reported as potential therapeutic targets and potential prognostic biomarkers for several cancers." (PMID 41011134, 2025). "Among all proteins that showed a significant pro-tumoral effect, the interleukin-1 receptor accessory protein (IL-1RAP) appears as a valuable target for several kinds of cancers." (PMID 36499246, 2022). "We first studied the effects of IL1RAP silencing on migration and invasion of gastric derived cancer cells." (PMID 35488454, 2022). "In contrast to the well-studied IL1, many other molecules especially IL1RAP, its functions in infectious disease and cancer including KSHV infection and related diseases remain largely unclear." (PMID 36457850, 2022). "IL1RAP has been shown to be overexpressed in various cancer subtypes and even suggested to play a role in disease relapse." (PMID 35488454, 2022). "Two individual genes of module 6 were associated with treatment response, with IL18R1 being associated with good treatment response and IL1RAP being associated with poor response, in agreement with previous biological understanding of the IL18 and IL1 axes in cancer therapy." (PMID 38480759, 2024). "Most of these proteins are recognized as potential prognostic biomarkers in liver (TFRC and GPLD1), renal (IGHG1, PRCP, SAA1/2, and IL1RAP) and digestive (PRSS3) cancers in the Human Protein Atlas database." (PMID 41155404, 2025). "IL1RAP-CART cells react in the presence of IL1RAP+ cell lines or primary CML cells, resulting in secretion of proinflammatory cytokines and specifically killing cancer cells in vitro and in murine cancer xenograft models." (PMID 34202907, 2021). "As observed in the case of tongue, genes associated with overall cohort, IL1RAP, ANO1, RYK, AP2M1, MFN1 and PSMD2 were significant prognosticators only in the late stage not in early cancers." (PMID 31310629, 2019). "For example, CCR1, IL1RAP, CCL22 and CSF1 are all involved in metastatic dissemination, and their aberrant expression correlates with leukocyte infiltration and aggressive phenotype in various cancer types." (PMID 26536459, 2015). "But IL1RAP (p = 4.234 × 10−11), CXCL3 (p = 0), CXCL5 (p = 0), and CXCL6 (p = 0) gene expression levels had higher expression in ER-negative than ER-positive ones; whereas IL6ST was the only gene whose expression was higher in ER-positive cancer patients (p = 0)." (PMID 39201290, 2024).
infection (8 papers, 2013 to 2025). The state of being infected such as from the introduction of a foreign agent such as serum, vaccine, antigenic substance or organism. "For example, Interleukin 1 Receptor Accessory Protein (IL1RAP) gene was significantly down-regulated five days pre-infection (padj < 0.05) in cattle that showed the symptoms after challenge (susceptible) but was up-regulated three dpi in the same animals." (PMID 40665438, 2025). "In ileum inflammatory genes were overexpressed (e.g., IL-1B, IL-6, IL-8, IL1RAP, TNFα), indicating a strong immune response at all times of infection." (PMID 26738723, 2016). "Differential expression of IL1RAP show subsequent enrichment for the cytokine-cytokine receptor interaction pathway with five other DEGs (padj < 0.05) between symptomatic animals on seven dpi compared to pre-infection time." (PMID 40665438, 2025). "IL1RAP was thus differentially expressed at each time point post-infection versus pre-infection." (PMID 40665438, 2025). "However, there was a severe impairment in neutrophil recruitment to the site of infection in Il1rap KO mice." (PMID 39446964, 2024). "In contrast, infection downregulates the expression of Junb, involved in transcriptional cell growth regulation, the Jund gene mediating differentiation, and the interleukin 1 receptor accessory protein Il1rap gene, implemented in a dampening of an excessive inflammation." (PMID 37669943, 2023). "Notably, the expression of IL1R2 was down-regulated in mutant-infected cells compared to WT-infected cells, while IL1RAP expression was slightly up-regulated by the mutant infection." (PMID 37513744, 2023). "We also found that KSHV de novo infection of primary endothelial cells increased the levels of IL1 signaling molecules, such as IL1β, IL1R1, IL1RAP, IL36α and IL36γ." (PMID 36457850, 2022). "Similarly, our study using Il1rap KO mice which only had a defect in neutrophil recruitment to the site of infection suggests that neutrophils are not necessary for T. gondii control or IFN-γ production." (PMID 39446964, 2024).
cardiovascular diseases (3 papers, 2017 to 2024). "Our study highlights the potential benefits of targeting the IL1RAP-dependent cytokine pathways in patients with cardiovascular disease." (PMID 38563353, 2024). "We propose that blocking IL1RAP signalling, rather than an individual cytokine, may be more efficient in limiting leucocyte recruitment to the plaque and contributing to plaque stability in patients with elevated risk for cardiovascular disease." (PMID 38563353, 2024).
infectious disease (3 papers, 2018 to 2025). A disorder directly resulting from the presence and activity of a microbial, viral, or parasitic agent in humans. "When compared to children with various infectious diseases, only patients with KD showed up-regulation of two key receptors IL1-receptor (IL1R) and IL-1 receptor accessory protein (IL1RAP)." (PMID 30619331, 2018).
metabolic disease (2 papers, 2023 to 2025). A congenital disorder (due to inherited enzyme abnormality) or acquired (due to failure of a metabolically important organ) disorder resulting from an abnormal metabolic process. "In metabolic diseases such as T2D and IR, IL1RAP has been described to be involved in the macrophage-mediated chronic inflammatory response." (PMID 38139277, 2023).
digestive system cancer (1 paper, 2022). A primary or metastatic malignant neoplasm involving any part of the digestive system. "In this study, three of these four differentially methylated genes have been reported to be associated with digestive system cancers (USP1, CDH4, and IL1RAP)." (PMID 36685967, 2022).
IL1RAP also shares sentences with these, for which no sentence is quoted: schizophrenia (3 papers); triple-negative breast carcinoma (3); Arthritis (2); endometriosis (2); heart failure (2); Hypertension (2); lung cancer (2); myelodysplastic syndrome (2); neurological disorders (2); non-small cell lung carcinoma (2); pancreatic ductal adenocarcinoma (2); rheumatoid arthritis (2); acne (1); acute myocardial infarction (1); adenocarcinoma (1); alcoholism (1); allergic conjunctivitis (1); amyloid (1); autoimmune disease (1); autoimmune myocarditis (1); bacterial infections (1); breast invasive carcinoma (1); bronchitis (1); childhood asthma (1); cognitive deficits (1); colon cancer (1); colorectal cancer (1); Crohn disease (1); depression (1); haematological disease (1).
A further 25 diseases each share a sentence with IL1RAP in 1 paper.